CD68 (CD68 molecule)
Diseases named in the same sentence as CD68 in open-access papers (continued):
Sharing a sentence is not in itself a finding about the gene and the disease.
angiosarcoma (5 papers, 2007 to 2021). A malignant tumor arising from the endothelial cells of the blood vessels. "The tumor cells were negative for desmin, HHF35, HMB45, Melan A, MITF, c-kit, DOG1, cytokeratin AE1/AE3, h-caldesmon, STAT6, CD68, CD31, Factor 8, and ERG, making diagnoses of PEComa, GIST, SFT, and angiosarcoma unlikely." (PMID 34797454, 2021). "Although CD8 staining of the lining cells in splenic angiosarcoma has been reported, the main endothelial cell markers, including CD31, CD34, factor VIII–related antigen, and the histiocytic marker CD68, should exhibit strong positivity." (PMID 29378604, 2018). "Conversely, testicular angiosarcomas showed negative immunoreactivity to Pancytokeratin, AE1-AE3, Placental Alkaline Phosphatase, CD68, and Leucocyte Common Antigen in all the cases in which they was used." (PMID 17601346, 2007).
cerebral aneurysms (5 papers, 2018 to 2024). "Other previous studies revealed some association of CD68 with cerebral aneurysm formation and rupture." (PMID 38553592, 2024). "The histological and radiological inflammatory findings observed in the wall of cerebral aneurysms, as well as the CD68 positivity, are significantly associated with the risk of intracranial aneurysm growth and rupture." (PMID 37744724, 2023). "Accumulation of CD68+ macrophages in cerebral vessels is a sign of wall vessel damage in cerebral aneurysms." (PMID 38469142, 2024). "Consistent with our findings in the walls of human IA, phospho-FAK and CD68 signals were increased in the cerebral aneurysms walls of Vehicle group compared with those of sham group." (PMID 29899701, 2018).
cholestasis (5 papers, 2017 to 2022). Impairment of the bile flow caused by obstruction within the liver, or outside the liver in the bile duct system. "In line with the previous observations, RIO treatment significantly decreased CD68+ area in rats with advanced cholestasis." (PMID 29921982, 2018). "The characterization of NPCs in suspension using flow cytometry demonstrated that the proportion of CD68+ cells in the control liver tissues was on average 10%, in contrast to a more than two times higher proportion of CD68+ cells in the case of one donor with bile duct carcinoma and cholestasis." (PMID 33918803, 2021). "To further investigate the role of inflammation in the development of cholestasis in MDR2KO mice, we looked first at recruited monocytes/macrophages expressing CD68 and F4/80, which are known to be present in cholestatic liver using IHC." (PMID 29125588, 2017). "The patient with bile duct carcinoma and cholestasis (D29) showed the largest number of CD68+ cells without an inflammatory state." (PMID 33918803, 2021). "Immunofluorescence assays of CD68+ macrophages and CK-19-expressing cholangiocytes in the livers of naïve and GWI rats subjected to sham or BDL surgeries demonstrated a significant increase in the amount of these macrophages after BDL-induced cholestasis." (PMID 30177688, 2018).
colon adenocarcinoma (5 papers, 2018 to 2025). "However, in colon adenocarcinoma, SALL2 expression decreased in both cell types and increased in type 1 macrophages (CD68+)." (PMID 40869218, 2025).
Crohn disease (5 papers, 2013 to 2024). A gastrointestinal disorder characterized by chronic inflammation involving all layers of the intestinal wall, noncaseating granulomas affecting the intestinal wall and regional lymph nodes, and transmural fibrosis. "Two cases of infectious mononucleosis exhibited similar numbers of CD68+pSTAT1+ and of CD68+CMAF+ macrophages (M1 ≈ M2) while one case of Crohn’s disease displayed an M2>M1 pattern." (PMID 24260507, 2013).
cutaneous melanoma (5 papers, 2017 to 2025). A primary melanoma arising from atypical melanocytes in the skin. "MIS and invasive primary cutaneous melanoma had higher COX2+ CD68+ cells compared to metastatic lesions and benign nevi." (PMID 39825956, 2025). "Comparison of macrophage infiltration levels across different pT stages of cutaneous melanoma revealed a consistent upward trend in both intratumoral and peritumoral CD68+ macrophage counts as the tumor stage advanced." (PMID 41007741, 2025). "Despite significant progress in understanding the role of macrophages in cutaneous melanoma, the quantitative characteristics of CD68+ and CD163+ cells at different stages of the disease remain insufficiently studied." (PMID 41007741, 2025). "An analysis of macrophage infiltration in cutaneous melanoma based on tumor thickness according to the Breslow scale revealed a clear trend toward an increase in both intratumoral and peritumoral numbers of CD68+ and CD163+ macrophages with tumor progression." (PMID 41007741, 2025). "This study aimed to quantitatively assess CD68+ and CD163+ macrophages in the intratumoral and peritumoral stroma of cutaneous melanoma at different stages of the disease." (PMID 41007741, 2025). "The results of this study demonstrate a clear increase in both CD68+ and CD163+ macrophage infiltration in cutaneous melanoma tissues as tumor thickness and stage progress." (PMID 41007741, 2025). "Immunohistochemical staining revealed the presence of CD68+ and CD163+ macrophages in both intratumoral and peritumoral compartments of cutaneous melanoma samples." (PMID 41007741, 2025). "In addition, the spatial transcription data on SpatialDB showed that RAB5B spatially overlapped with endothelial cell markers PECAM1 and VWF in BCC cancer tissues and M2 macrophage markers CD68 and CD163 in skin melanoma tissues." (PMID 40842984, 2025). "This study aims to address this gap by providing a comprehensive analysis of CD68+ and CD163+ macrophages in cutaneous melanoma stages I–III, which may be critical for elucidating the mechanisms of tumor progression." (PMID 41007741, 2025).
delirium (5 papers, 2014 to 2023). A disorder characterized by confusion; inattentiveness; disorientation; illusions; hallucinations; agitation; and in some instances autonomic nervous system overactivity. "In a postmortem case–control study, microglial activation was found to be associated with delirium, and the expression of microglial markers CD68 and HLA-DR was significantly elevated in patients with delirium compared with that in controls." (PMID 37891821, 2023). "In a postmortem case-control study of patients with delirium, the expression of microglial markers CD68 and HLA-DR were significantly increased compared to that in the controls, suggesting that microglial activation may be associated with delirium." (PMID 35958583, 2022). "LM‐ and AS‐induced delirium led to microglial activation in the hippocampus as evidenced by up‐regulation of microglial activation‐related genes (such as Il6ra, Tyrobp, Cd68, Aif1, Csf1r, and Trem2) and of relevant inflammatory factors (such as Il‐1β, Tnfα, Ccl2, Ccl5, and Ccl8)." (PMID 35713240, 2022). "Similarly, in a postmortem case-control study of patients with delirium, there was an increase in microglial markers CD68 and HLA-DR compared to age-matched controls, suggesting that microglia activation could be related to delirium." (PMID 34062710, 2021).
diffuse large B-cell lymphoma (5 papers, 2015 to 2024). "The data showed that prostate adenocarcinoma (PRAD) and diffuse large B-cell lymphoma had a high mutation level with CD68 deep deletion of more than 4%." (PMID 35550532, 2022). "The presence of RCAS1 protein immunoreactivity was demonstrated in 65 % of the examined tissue samples of diffuse large B-cell lymphoma and in 25 % of the analyzed stromata in which it was exhibited by CD68-positive cells identified as macrophages and dispersed throughout the stroma." (PMID 25773455, 2015). "The current work tracked immunohistochemistry marker CD4, CD8, CD68, and MMP9 staining in diffuse large B cell lymphoma cases." (PMID 35083113, 2022). "used a customized panel of 36 antibodies for DSP from samples of diffuse large B-cell lymphoma (DLBCL) patients pretreated with chemoimmunotherapy and revealed that CD68+CD163+ M2 macrophages showed dramatic negative impacts on prognosis." (PMID 36389765, 2022).
Ewing sarcoma (5 papers, 2007 to 2025). A small round cell tumor that lacks morphologic, immunohistochemical, and electron microscopic evidence of neuroectodermal differentiation. "CD68 and CD99 can be positive in a subset of the cases presenting a potential diagnostic challenge especially in differentiating from Ewing’s sarcoma." (PMID 36225497, 2022). "A total of 41 patients with Ewing’s sarcoma were divided into two groups according to the density of CD68+ macrophages: 21 patients (51%) with lower infiltration (≤30 CD68+ cells/HPF) and 20 patients (49%) with higher infiltration (>30 CD68+ cells/HPF)." (PMID 33802565, 2021). "Further analyses based on the larger cohorts are necessary to clarify the prognostic role of CD68+ and CD163+ macrophage density in Ewing’s sarcoma." (PMID 33802565, 2021). "Fibroblasts isolated from Ewing's sarcomas and bone stromal cells consisted almost entirely of spindle-shaped mononuclear cells, which did not stain immunohistochemically for CD99, CD14 or CD68 or VNR and TRAP." (PMID 17533390, 2007).
gastric adenocarcinoma (5 papers, 2023 to 2025). "The infiltration of CD68+/CD163- macrophages has been identified as a poor prognostic factor following neoadjuvant chemotherapy in EC and gastric adenocarcinoma." (PMID 40746552, 2025). "Immunohistochemistry (IHC) was utilized to assess PD-L1 expression and TIIC markers (CD3, CD4, CD8, CD19, CD31, CD68, CD11c, CD56, and α-smooth muscle actin) in gastric adenocarcinoma tissues from 268 patients." (PMID 38050283, 2023).
glomerulosclerosis (5 papers, 2015 to 2025). A hardening of the kidney glomerulus caused by scarring of the blood vessels. "The areas stained for glomerulus and tubular damage (tubular atrophy, interstitial inflammation, glomerular sclerosis, interstitial fibrosis), CD3e, CD68, and COL1α1 were significantly reduced after GQDs pre‐treatment." (PMID 39739624, 2025). "We included age, sex, baseline serum creatinine, glomerular CD68+ cell number, and percentage of glomerulosclerosis in the multivariate regression model." (PMID 40338344, 2025). "Most of the clinical and histological findings were comparable between progressors and non-progressors, while progressors had a higher median number of glomerular CD68+ cells and a higher percentage of glomerulosclerosis." (PMID 40338344, 2025). "In general, the density of CD68-positive cells was in parallel to the severity of structural damage including glomerulosclerosis, arteriosclerosis, and interstitial fibrosis." (PMID 25918729, 2015). "However, the median number of glomerular CD68+ cells (HR 1.27, 95% CI 1.03–1.57, p = 0.029) and percentage of glomerulosclerosis (HR 9.25, 95% CI 1.23–69.37, p = 0.030) were predictors of progression." (PMID 40338344, 2025). "Compared to the vehicle control mice, Ac-FLTD-CMK-treated MRL/lpr mice had a lower urine albumin-creatinine ratio, a lower serum creatinine concentration, reduced glomerulosclerosis and CD3, CD4 and CD68 positive cell infiltration." (PMID 34867948, 2021).
Hepatitis (5 papers, 2013 to 2024). Inflammation of the liver. "In the case of Concanavalin-A-induced hepatitis, the ROS produced by CD68+ Kupffer cells is the final effector, while the TNF produced by CD11b+ Kupffer cells/Mφ and NKT cells is needed to activate and increase the CD68+ Kupffer cells." (PMID 26333171, 2015). "TNF-α, IL1β and IL-6 are the cytokines most commonly associated with liver inflammation, while CD64 and CD68 are markers of Kupffer cell activation." (PMID 23755290, 2013). "We also conducted double labeling of CCL20 and CXCL8 with CD68 and CD3, respectively, on liver biopsy samples from HBeAg‐positive hepatitis patients." (PMID 39135698, 2024). "FasL-expressing NKT cells and ROS-producing CD68+ Kupffer cells, both activated by the TNF produced by CD11b+ Kupffer cells, are the final effectors in these hepatitis models." (PMID 24667392, 2014). "In contrast to the hepatic injury induced by either α-GalCer or CpG-ODN, CD68+ Kupffer cells and their ROS production induced by the TNF produced by CD11b Kupffer cells/macrophages are the final effectors in Con-A-induced hepatitis." (PMID 24667392, 2014).
HIV-1 infection (5 papers, 2011 to 2023). The type species of lentivirus and the etiologic agent of acquired immunodeficiency syndrome (AIDS). "It is also possible that hBD-2PTD and/or hBD-3PTD may inhibit HIV-1 infection in CD4+ T lymphocytes, CD68+ macrophages, and CD1c+ DC in the tonsil tissue." (PMID 34696473, 2021).
Hydrocephalus (5 papers, 2019 to 2022). Hydrocephalus is an active distension of the ventricular system of the brain resulting from inadequate passage of CSF from its point of production within the cerebral ventricles to its point of absorption into the systemic circulation. "Moreover, epiplexus cell activation in rat CP characterized by increased number of CD68+ and Iba-1+ cells as well as Iba-1+ cell soma size was associated with the development of hydrocephalus 24 h after SAH induction." (PMID 32116563, 2020). "CD68, as a marker of activated macrophages, has been used to indicate macrophage participation in hydrocephalus development." (PMID 35216420, 2022). "Aged rats had more prominent hydrocephalus as well as an increased amount of Iba-1 and CD68 immuno-positive macrophages on day 1 after intraventricular iron injection compared with young rats." (PMID 32106865, 2020). "Because CD68-positive macrophage invasion into the periventricular region was seen in P5 mutants before the subarachnoid hemorrhage started, the inflammatory reaction is primarily a result of the hydrocephalus insult." (PMID 31771992, 2019).
Hyperglycemia (5 papers, 2011 to 2024). An increased concentration of glucose in the blood. "We also found that hyperglycaemia tended to be correlated with CD68 expression, which is a marker of microglial activation." (PMID 21612615, 2011). "This may explain that hyperglycaemia tended to be correlated with microglial activation (reflected by CD68 expression), which is prior to apoptosis." (PMID 21612615, 2011).
invasive ductal carcinoma (5 papers, 2012 to 2025). "Immunostainings for CD3, CD20 and CD68 were performed in TMA blocks from invasive ductal carcinoma of the breast, showing a membranous staining for CD3 and CD20, whereas CD68 staining is found in the cytoplasm." (PMID 23300781, 2012).
leukemia (5 papers, 2013 to 2025). A malignant (clonal) hematologic disorder, involving hematopoietic stem cells and characterized by the presence of primitive or atypical myeloid or lymphoid cells in the bone marrow and the blood. "Nonetheless, these observations collectively suggest leukemia-specific proximity of CD74+CD68+ cells and CD34+ primitive cells, and a potential support role for RECs in AML regeneration that forms the basis of functional testing." (PMID 38582086, 2024). "Similarly, in a study by Dander E and colleagues in patients with B-ALL, an increase in CD68-expressing macrophages was reported in BM biopsies with leukaemia compared to controls." (PMID 39676870, 2024). "CD68 epitopes have been suggested as a potential target for leukemia-reactive cytotoxic-T cell." (PMID 23476896, 2013). "Moreover, using a human leukemia model, IL-34 enhanced the differentiation of leukemia cells into differentiated macrophages by means of an increase in CD14 or CD68 and a decrease in CD71, a cell surface marker for immature myeloid cells." (PMID 33408768, 2021). "CD34+ areas had higher CD74 and CD68 expression as compared with CD34− areas, while this pattern was absent in healthy tissues, confirming a leukemia-specific proximity of RECs and CD34+ cells." (PMID 38582086, 2024).
lung disease (5 papers, 2007 to 2017). "In both LRI of infancy and advanced lung disease associated with CF, cell-associated A1PI and the macrophage marker CD68 appeared colocalized in sequential sections, consistent with macrophage expression of A1PI." (PMID 23226468, 2012). "Accordingly, the CD68-rtTA system can be exploited to target-specific lung tissue macrophage populations and to distinguish the roles they play during both homeostasis and in lung disease." (PMID 29225599, 2017).
lupus (5 papers, 2012 to 2024). "The expression of markers of T cells (CD4, CD8α), B cells (CD19) and macrophages (CD68) was elevated in PVAT from lupus mice." (PMID 37006244, 2023). "The density of CD68-positive macrophages in both glomerular and extraglomerular areas was greatly increased in lupus patients." (PMID 22640796, 2012). "CD68-positive macrophages were identified in the mesangial areas of both normal and lupus glomeruli, as well as in extraglomerular areas." (PMID 22640796, 2012). "Kidney biopsies from 58 patients with systemic lupus erythematosus (SLE) proliferative nephritis were analyzed with immunohistochemistry (IHC) for intravascular platelet aggregates (CD61), macrophagic infiltration (CD68), and activated complement deposition (C4d)." (PMID 22640796, 2012). "In the tubulointerstitium there was positive correlation between a higher TSI and the number of total CD68+ macrophages (r = 0.328) but also with the number of M2a-like (r = 0.446) and M2c-like macrophages (r = 0.420) when correlation with the TSI was tested independently of ISN/RPS lupus class." (PMID 27091114, 2016).
mesothelioma (5 papers, 2014 to 2024). A usually malignant and aggressive neoplasm of the mesothelium which is often associated with exposure to asbestos. "It has been demonstrated that a high density of CD68+ macrophages in surgical mesothelioma samples was correlated with worse patient clinical outcome and their depletion with zoledronic acid strongly reduced tumor growth in mouse mesothelioma models." (PMID 33050070, 2020). "The percentage of M2 macrophages of the total macrophage count was comparable between the surgery and non-surgery group and therefore, the CD163/CD68 ratio does not discriminate in favor of surgery in mesothelioma patients." (PMID 25192022, 2014).
multiple sclerosis (5 papers, 2005 to 2025). A progressive autoimmune disorder affecting the central nervous system resulting in demyelination. "Although we did not examine the expression of C1q in microglia, we studied the expression of CD68 expression in microglia since C3-positive reactive astrocytes have been found to be in close association with CD68-positive microglia in other neurodegenerative diseases such as multiple sclerosis." (PMID 38025259, 2023). "These include, for example, marker genes for disease-associated microglia (DAM), the microglia neurodegenerative phenotype (MGnD), and microglia inflamed in multiple sclerosis (e.g., APOE, CLEC7A, TREM2, CD68)." (PMID 40700130, 2025). "It has been shown that in multiple sclerosis, YKL-40 is expressed by macrophages/microglial cells (CD68+) in low and high inflammatory activity lesions." (PMID 28599675, 2017). "TMEM119 reliably stains microglia in the human brain, while macrophages (Iba1+/CD68+) at sites of necrotic lesion in human multiple sclerosis (MS) brains do not express TMEM119." (PMID 30241479, 2018).
nasopharyngeal carcinoma (5 papers, 2021 to 2024). A carcinoma arising from the nasopharyngeal epithelium. "All subtypes of nasopharyngeal carcinoma presented with an inflammatory infiltrate with numerous plasma cells, eosinophils, and dendritic cells, presenting as antigen CD1a- and CD68-positive, as well as in CD117-positive mast cells." (PMID 38611634, 2024). "However, other meta-analysis, has revealed high CD68+ TAM densities were associated with worse overall survival and disease-free survival in nasopharyngeal carcinoma (NPC) patients." (PMID 37397243, 2023). "In nasopharyngeal carcinoma (NPC), HLA-G is positively correlated with CD68+ macrophages and IL-10 expression, indicating that HLA-G may regulate immune escape in NPC." (PMID 34868081, 2021).